ADAM17 (ADAM metallopeptidase domain 17)
Diseases named in the same sentence as ADAM17 in open-access papers (continued):
Sharing a sentence is not in itself a finding about the gene and the disease.
gastric cancer (continued). "CD147 expression mediates gastric cancer cell proliferation and invasion via the ERK1/2 signaling pathway and is up-regulated in gastric cancer lesions in correlation with ADAM17." (PMID 25268615, 2014). "In gastric cancer the expression of ADAM10, ADAM15, ADAM17 and ADAM 20 transcripts is markedly increased." (PMID 25437333, 2013). "Both gastric ADAM17, and EGFR ligands HB-EGF, amphiregulin and EGF, are increased in patients with H. pylori infection and/or gastric cancer and are likely to contribute to epithelial hyperplasia." (PMID 25437333, 2013). "As a proof-of-concept pilot study, the expression of ADAM8, ADAM9, ADAM10, ADAM12, ADAM17, and major histocompatibility complex (MHC) class I chain-related sequence A (MICA), a ligand for NKG2D, in gastric cancer was investigated in silico using The Cancer Genome Atlas (TCGA) database." (PMID 39755747, 2025). "In the previous meta-analysis, it only explored the relationship between ADAM17 expression and clinicopathological parameters in stomach cancer but did not assess the prognostic value of ADAM17." (PMID 32610677, 2020). "Elevated expression of ADAM17 is positively correlated with CD147 expression due to its activation of EGFR in gastric cancer, especially in lesions, compared to adjacent non-cancerous tissues." (PMID 25268615, 2014). "Moreover, in gastric cancer cells, ADAM10 and ADAM17 are pulled down together by RECK - suggesting a physical interaction between RECK and ADAMs at the cell surface." (PMID 25246708, 2014). "Since the EGFR transactivation requires ADAM10, rather than ADAM17, for shedding the ectodomain of EGFR ligands, IL-8 dose-dependently released the EGFR ligands in human gastric cancer cells in vitro." (PMID 36572816, 2023). "A previous meta-analysis showed ADAM17 was correlated with TNM stages and distant metastasis, but not correlated with cancer grade of stomach cancer." (PMID 32610677, 2020). "In vitro studies with human MKN-28 gastric cancer cells have shown H. pylori induced upregulation of COX-2 and HB-EGF, but not ADAM17, is reduced by EKB-569 treatment." (PMID 25437333, 2013).
rheumatoid arthritis (26 papers, 2013 to 2025). A chronic, systemic autoimmune disorder characterized by inflammation in the synovial membranes and articular surfaces. "The family member ADAM17 has been linked in particular to chronic inflammatory processes such as rheumatoid arthritis." (PMID 36078095, 2022). "Compound 37 (SCH900567), a hydantoin derivative with ADAM17 inhibitory activity, has been explored as a potential treatment for rheumatoid arthritis." (PMID 41050403, 2025). "In the context of autoimmune diseases, aberrant ADAM17 activity has been linked to elevated TNF-α levels and chronic inflammation in conditions such as rheumatoid arthritis (RA), systemic lupus erythematosus (SLE), psoriasis, and Crohn’s disease." (PMID 41050403, 2025). "Increased TNF-α release is clearly correlated with dysregulated ADAM17 activity in autoimmune conditions, such as rheumatoid arthritis (RA), SS, systemic lupus erythematosus (SLE), psoriasis, and Crohn’s disease (CD)." (PMID 39768182, 2024). "For example, genetic associations have been observed between elevated plasma levels of ADAM-17 and rheumatoid arthritis." (PMID 38892098, 2024). "This understanding would significantly influence tackling chronic and life-threatening diseases, which were found to be connected to ADAM17, such as cancer and chronic inflammatory diseases like rheumatoid arthritis." (PMID 35163294, 2022). "Two of the metalloprotease inhibitors tested in our study, DPC‐333 and apratastat, were developed to block ADAM17‐mediated TNFα shedding and previously entered phase 2 clinical trials for the treatment of the inflammatory joint disorder rheumatoid arthritis." (PMID 35527514, 2022). "TMI-005 is an oral small molecule inhibitor of ADAM17 and has been studied in various inflammatory conditions including Rheumatoid Arthritis." (PMID 35095853, 2021). "TNF levels are increased in most chronic inflammatory diseases, supporting the involvement of ADAM17 in their progression, including rheumatoid arthritis (RA)." (PMID 33579029, 2021). "Ablation of ADAM17 in myeloid cells is protective against rheumatoid arthritis to a similar extent as the ablation of TNF." (PMID 33579029, 2021). "Increased tissue ADAM17 expression has been reported in different immune-mediated inflammatory diseases, including rheumatoid arthritis, psoriasis and inflammatory bowel disease highlighting its role in mediating downstream injury/inflammation." (PMID 35095853, 2021). "ADAM17 inhibitors can inhibit tumor necrosis factor alpha (TNFα) shedding, and early inhibitors had efficacy in rheumatoid arthritis models." (PMID 29230082, 2017). "Not unexpectedly, selective small molecular inhibitors of ADAM17/TACE have also been studied for their potential use as a future therapy for rheumatoid arthritis." (PMID 29276788, 2017). "In autoimmune diseases, the dysregulation of ADAM17 activity may lead to an imbalance in immune responses, exacerbating conditions such as rheumatoid arthritis and multiple sclerosis." (PMID 40143211, 2025). "This selectivity could be especially relevant in chronic inflammatory diseases such as rheumatoid arthritis and systemic lupus erythematosus glomerulonephritis, where dysregulated ADAM17–iRhom2 activity plays a critical role." (PMID 40512800, 2025). "While the small chemical entities had side effects such as musculoskeletal and liver toxicities, they provided proof of concept experiments indicating that targeting ADAM17 would be beneficial for disease conditions such as sepsis and rheumatoid arthritis (RA)." (PMID 29230082, 2017). "Since ADAM17 processes so many substrates, side effects may occur which would preclude its use for rheumatoid arthritis and inflammatory bowel disease." (PMID 29230082, 2017).
rheumatoid arthritis (continued). "ADAM17 inhibitors have broad therapeutic potential, with properties ranging from tumor immunosurveillance and overcoming drug and radiation resistance in cancer, as treatments for cardiac hypertrophy and inflammatory conditions such as inflammatory bowel disease and rheumatoid arthritis." (PMID 29230082, 2017). "TIMP-3 has been proven beneficial in diseases such as rheumatoid arthritis, which is majorly driven by an excess activity of TIMP-3 target ADAM17, and osteoarthritis, which is characterized by cartilage breakdown due to ADAMTS-4 and -5." (PMID 36013323, 2022). "Thanks to its broader inhibitory profile, TIMP-3 has been proven beneficial in diseases such as rheumatoid arthritis, which is majorly driven by an excess activity of TIMP-3 target ADAM17, and osteoarthritis, which is characterized by cartilage breakdown due to ADAMTS-4 and -5." (PMID 36013323, 2022). "Because of its ambivalent role, general inhibition of ADAM17 does not appear to be reasonable in the treatment of chronic inflammatory diseases such as rheumatoid arthritis or IBD." (PMID 34930929, 2021). "TACE, also known as ADAM17, plays a crucial role in the inflammatory response by converting pro-TNF-α to its active soluble form and cleaving other inflammatory mediators, making it a promising target for therapeutic intervention in diseases such as rheumatoid arthritis." (PMID 39729480, 2024).
Insulin resistance (24 papers, 2011 to 2025). Increased resistance towards insulin, that is, diminished effectiveness of insulin in reducing blood glucose levels. "An increase in ADAM17 expression was previously shown to be positively associated with the development of insulin resistance." (PMID 39859443, 2025). "Increased expression of ADAM17, disintegrin and metalloproteinase domain-containing protein 17, is associated with the development of insulin resistance and hepatosteatosis." (PMID 39003492, 2024). "Ablation of TIMP-3 in mouse, and subsequent loss of ADAM17 inhibition, leads to arthritis, chronic hepatic inflammation, insulin resistance, and liver/heart failure due to excessive release of tumor necrosis factor (TNF)." (PMID 33673623, 2021). "In omental AT of patients with morbid obesity, ADAM17 is considered a predictor of insulin resistance." (PMID 40806445, 2025). "ADAM17 has been shown to cleave the ectodomain of the insulin receptor, which can result in insulin resistance." (PMID 38963109, 2024). "In the milieu of T2DM, elevated chronic plasma levels of TNF-α, a consequence of ADAM17's shedding activity, promote insulin resistance, thereby decreasing the activation of the PI3K/AKT pathway." (PMID 38963109, 2024). "Further upregulation of IRS-1, SIRT1, GLUT-4 and downregulation of ADAM17, demonstrated its potential impact on glucose homeostasis, insulin resistance and chronic inflammatory markers." (PMID 37089941, 2023). "The pro-inflammatory state induced by ADAM17 led to glucose intolerance and insulin resistance in HFD mice." (PMID 35008648, 2021). "Recent research has shown that EC ADAM17 can cleave the insulin receptor ectodomain, leading to cellular insulin resistance, which could exacerbate insulin resistance, with the initial upregulation of ADAM17 potentially leading to further GSK3β activation." (PMID 37762417, 2023). "Several reports support the relationship between ADAM17 and insulin resistance." (PMID 35008648, 2021). "ADAM17 expression is significantly increased in the liver and adipose tissue of mice that have been fed HFD and it is positively associated with the development of insulin resistance and hepatosteatosis." (PMID 33904577, 2021). "On the other hand, lower ADAM-17 levels may have a clinical linkage with insulin resistance in POAF patients." (PMID 32451455, 2020). "Similarly, the activity of ADAM17, also known as TNF-α converting enzyme (TACE), correlates with insulin resistance and administration of TACE inhibitors to humans in clinical trial settings has proven to effectively decrease inflammatory mediators." (PMID 28265178, 2017). "By altering the balance between IL-1R1 and its decoy receptor IL-1R2, ADAM17 enhances sensitivity to IL-1, leading to the activation of nuclear factor-kappa B (NF-κB) and promoting a major pro-inflammatory pathway, contributing to the pathogenesis of insulin resistance." (PMID 38963109, 2024). "ADAM17 (TACE-TNF-α converting enzyme) is the enzyme responsible for the conversion of TNF-α, and its high expression is correlated with insulin resistance development." (PMID 39273582, 2024). "In humans, ADAM17 expression and enzymatic activity were increased in T2DM skeletal muscle, as were the substrates TNF-α and IL6-R, which positively correlated with insulin resistance." (PMID 38963109, 2024). "The activation of GSK3β in ECs after insulin resistance upregulates VCAM1 expression, and VCAM1’s ectodomain is cleaved by the metalloproteases ADAM10 and ADAM17, which also show increased expression in diabetic ECs." (PMID 37762417, 2023). "Ablation of TIMP-3 in mouse enhanced inflammation by dysregulating the activity of ADAM17 (a TIMP-3 target metalloproteinase) and the subsequent release of its substrate TNF, thus promoting insulin resistance and hepatosteatosis." (PMID 33673623, 2021). "Furthermore, ablation of TIMP-3 and subsequent dysregulated ADAM17 activity and TNF release promoted insulin resistance and hepatosteatosis." (PMID 33579029, 2021).
melanoma (23 papers, 2012 to 2025). A malignant, usually aggressive tumor composed of atypical, neoplastic melanocytes. "Since it has been recently shown that the activation of ADAM17 by IL-15 limits human NK cell proliferation, we propose that cleavage of the mbIL-15 by ADAM17 causes the spread of a soluble biological active complex within the melanoma TME." (PMID 37334356, 2023). "In agreement with the results from melanoma tumor model, ADAM17 deficiency in T cells showed a superior anti-tumor activity than WT controls, which also demonstrated an intrinsic role of ADAM17 in CD8+ T cell function." (PMID 38918390, 2024). "By blocking the ADAM17/EGFR/AKT/GSK3β pathway, RA prevents invasive proliferation and migration of human melanoma A375 cells, induces apoptosis, and increases the susceptibility of melanoma cells to cisplatin." (PMID 40427522, 2025). "First, melanoma B16-F10 cells were inoculated directly onto ADAM17 WT (ADAM17fl/flLck-Cre-) and KO (ADAM17fl/flLck-Cre+) mice." (PMID 38918390, 2024). "In another study, RA showed an inhibitory effect on melanoma cells via suppression of the ADAM17/EGFR/AKT/GSK3β axis resulting in the inhibition of melanoma cell proliferation, invasion, and migration." (PMID 37687080, 2023). "A study has revealed that downregulation of SPAG5 suppresses the ADAM17/NOTCH1 pathway by lowering the expression of FOXM1 in malignant melanoma (MM), thereby dampening the viability, migration, invasion, and EMT of MM cells." (PMID 36118675, 2022). "RA possesses an inhibitory effect on melanoma cells’ proliferation, movement, and invasion via inhibiting expression of the ADAM17/EGFR/AKT/GSK3β axis." (PMID 36247004, 2022). "The ADAM17/EGFR/AKT/GSK3β axis plays a key role in regulating melanoma cell proliferation, migration, and cell sensitivity to chemotherapeutic drugs." (PMID 36466812, 2022). "In another study, anticancer effects of RA in A375 cells melanoma cells via downregulation of ADAM17 and expression of ADAM17/EGFR/AKT/GSK3β were also evaluated." (PMID 36247004, 2022). "The human melanoma A375 cells were exposed to RA, then cell viability, migration, invasion, apoptosis, melanin content and the expression of ADAM17/EGFR/AKT/GSK3β were evaluated." (PMID 34224305, 2021). "Previous studies indicated that high ADAM17 gene expression correlates with poor progression-free survival in melanoma patients." (PMID 34224305, 2021). "RA also down-regulated the expression level of ADAM17, EGFR, p-AKT and p-GSK3β in melanoma cells, suggesting that RA had the anti-cancer potential for melanoma treatment, and the underlying mechanism may be related to inhibiting the activation of ADAM17/EGFR/AKT/GSK3β axis." (PMID 34224305, 2021). "Our results fully proved that RA played a role of protecting melanoma cells against malignant metastasis by inhibiting ADAM17/EGFR/AKT/GSK3β axis." (PMID 34224305, 2021). "A further study was then conducted, where we used ADAM17 inhibitor-TPD to down-regulate the expression level of ADAM17 in melanoma cells." (PMID 34224305, 2021). "Results illustrated that RA can inhibit the expression of ADAM17 in melanoma cells and suppress cell proliferation, invasion, migration, and melanin synthesis as well as increasing apoptosis and Cis sensitivity." (PMID 34224305, 2021). "PMEL17 or GP100 is a type I integral membrane protein specifically expressed by melanocytes and melanoma cells that is processed by ADAM17." (PMID 29230082, 2017). "For example, the cytokine TNF-α, or L1 and CD44 adhesion molecules, are cleaved by ADMA10 and ADAM17 and released in EVs by ovarian cancer or melanoma cells." (PMID 25278937, 2014). "Therefore, we investigated the potential effect of NOX1 and ADAM17 inhibition on the generation of sMCAM by mouse melanoma and CRC cells." (PMID 38137406, 2023). "Furthermore, ADAM17 overexpression likewise increased proliferation and significantly decreased apoptosis levels of melanoma cells." (PMID 36293469, 2022).
melanoma (continued). "We aimed to investigate whether RA could exhibit anti-cancer effects in melanoma cells through down-regulating ADAM17." (PMID 34224305, 2021). "In accordance with our speculation, all the effects of RA on melanoma cells were significantly blocked by ADAM17 overexpression, but greatly enhanced by ADAM17 inhibition." (PMID 34224305, 2021). "In addition, rosmarinic acid enhanced cisplatin sensitivity of melanoma cells through mediating the ADAM17/EGFR/AKT/GSK3β axis." (PMID 34516354, 2021). "However, inhibition of ADAM17 with TPD further strengthened all the effects of RA on melanoma cells." (PMID 34224305, 2021). "As regards the molecular mechanism by which the mast cell proteases affect melanoma dissemination, our findings reveal that the absence of Mcpt4/Mcpt6/Cpa3 is associated with a decrease in ADAM17 expression." (PMID 28212574, 2017). "Furthermore, we up-regulated ADAM17 in melanoma cells using overexpressing vectors and illustrated that overexpression of ADAM17 significantly blocked the effect of RA on cellular proliferation, migration, invasion, apoptosis, melanin content, and Cis sensitivity of melanoma cells." (PMID 34224305, 2021). "Since AREG precursor protein is released extracellularly as soluble AREG ligand after cleavage by metalloprotease TACE/ADAM17, we next determined if AREG TM precursor is likewise secreted as AREG ligand by BAKP melanoma cells." (PMID 38727313, 2024). "For example, ADAM9 promotes the invasion and metastasis of cancer cells in melanoma by activating MMP1 and MMP2, while ADAM17 can activate MMP2 to treat the disease (prostate cancer and lung injury) by promoting angiogenesis." (PMID 36172139, 2022). "The presence of ADAM17 and ADAM10 active forms in vesicles has been also detected in melanoma and HIV-1 infected T cells." (PMID 25278937, 2014). "The shedding of EGFR ligands is mainly dependent on the metalloproteases ADAM-17 and ADAM10, the latter being induced by PAX2 in melanoma." (PMID 24970815, 2014). "Based on the results, we speculated that RA could target ADAM17 to down-regulate its expression therefore inactivate ADAM17/EGFR/AKT/GSK3β axis, ultimately exerting anti-cancer effects on melanoma in vitro." (PMID 34224305, 2021). "Additionally, ADAM17 was significantly overexpressed in advanced stage of melanoma, and the expression of TNF-α was up-regulated and significantly correlated with the expression of ADAM17 and respectively, with the advanced tumor stage." (PMID 34224305, 2021). "Since most ligands of the HER family need to be cleaved from the cell surface by sheddases, we analyzed the cell surface expression of the sheddases ADAM (a disintegrin and metalloprotease) domain 17 (TACE/ADAM17) and ADAM Metallopeptidase Domain 10 (ADAM10) on melanoma cells by flow cytometry." (PMID 33327495, 2020). "Therefore, we hypothesized that RA could down-regulate ADAM17 expression and inhibit EGFR/AKT signaling, thereby affecting the proliferation, migration and chemotherapy sensitivity of melanoma cells." (PMID 34224305, 2021). "Since TACE/ADAM17 and ADAM10 were shown previously to play an important role in ligand and receptor shedding, we analyzed A375 and SK Mel 28 melanoma cells and found that they expressed ADAM10 but not TACE/ADAM17." (PMID 33327495, 2020).